CAT (catalase)
Diseases named in the same sentence as CAT in open-access papers (continued):
Sharing a sentence is not in itself a finding about the gene and the disease.
Hypertension (81 papers, 2010 to 2025). The presence of chronic increased pressure in the systemic arterial system. "Eucommiae Folium treats hypertension through a multi-target and multi-pathway mechanism including epithelial sodium channel, heat shock protein 70, rho-associated protein kinase 1, catalase, and superoxide dismutase." (PMID 39468572, 2024). "Patients with acatalasemia and hypocatalasemia suffering from hereditary insufficient catalase activity are associated with several diseases, such as essential hypertension." (PMID 34501367, 2021). "Erythrocyte catalase activity tended to decrease in patients with hypertension and smoking as the major cardiovascular risk factors." (PMID 23631751, 2013). "Decreased blood catalase activity in this polymorphism together with low-level lead exposure induced lipid peroxidation may be responsible for hypertension." (PMID 25793211, 2015). "Our finding suggested that exposure to low lead level associated with oxidative stress and deficiency of the enzyme catalase may contribute to hypertension." (PMID 25793211, 2015). "Our findings suggested that decreased blood catalase activity in this polymorphism together with low level lead exposure induced lipid peroxidation may be responsible for hypertension." (PMID 25793211, 2015). "Similarly, we showed null associations between CAT and mMRC and heart disease and hypertension." (PMID 32977779, 2020). "Our findings are consistent with Pantopoulos (2018), who also reported decreased catalase enzyme activity in the plasma of patients with various degrees of essential hypertension." (PMID 40837913, 2025). "These processes appear to be NOX5- and redox-sensitive because NOX5 siRNA, melittin, SOD, and catalase attenuated responses in hypertension." (PMID 34320175, 2022). "Plasma catalase activity is decreased in patients with various stages of hypertension and treatment with anti-hypertensive drugs reverses this effect." (PMID 36290749, 2022). "It was suggested that equol elevated the activities of SOD, catalase, acetylcholinesterase, and glutathione peroxidase, and decreased the MDA levels in mice that had deoxycorticosterone acetate salt-induced hypertension and associated vascular dementia." (PMID 34835997, 2021). "The activity of extracellular antioxidant enzymes (such as SOD, glutathione peroxidase, and CAT) was significantly reduced in patients with moderate or severe hypertension compared to the control group." (PMID 35052583, 2021). "Based on renal functional and oxidative stress data, the current study demonstrated that apocynin provides more defence against oxidative stress, impaired kidney function and hypertension compared with catalase." (PMID 32298299, 2020). "Taken together, inhibiting NADPH oxidase by apocynin, catalase, and their combination prevents the onset of hypertension and renal injury induced by CsA." (PMID 32298299, 2020). "Treatment of CsA rats with apocynin, catalase, and their combination prevented hypertension and restored renal functional parameters and tissue Nox4 expression in this model." (PMID 32298299, 2020). "The novel finding of this study is that treatment of CsA renal injury rats with a combination of apocynin and catalase for 14 days ameliorated hypertension, renal dysfunction and oxidative stress." (PMID 32298299, 2020). "As the major cardiovascular enzymatic antioxidants, CAT indicates the role of oxidative stress in the hypertension." (PMID 23587307, 2013). "Among enzymatic defenses, catalase activity was profoundly altered by hypertension." (PMID 41300343, 2025). "Galangin, a flavonol, curtailed tissue markers of oxidative stress while enhancing catalase (CAT) activity, which subsequently contributed to the mitigation of hypertension inflicted by renal artery stenosis, alongside the associated cardiac and renal injuries in rats." (PMID 41333774, 2025). "Hypertension increased the concentration of malondialdehyde and decreased catalase activity in LV." (PMID 39337885, 2024).
Hypertension (continued). "Catalase overexpression reduces ROS generation and pro-fibrotic and apoptotic gene expression in the renal proximal tubular cells, which prevented hypertension, albuminuria, tubulointerstitial fibrosis, and tubular apoptosis in the mouse model of hypertension." (PMID 39456410, 2024). "Notably, catalase activity was enhanced 606% in the hypertension + exercise + diazoxide group, in contrast to the hypertensive group." (PMID 38653584, 2024). "However, in 140 hypertensive patients assessed with pedometers for 5 consecutive days, those with > 10,000 steps a day had significantly less oxidative stress (higher CAT and SOD levels and low malondialdehyde levels)." (PMID 37428393, 2023). "Interestingly, erythrocyte CAT activities are decreased in a manner which parallels the severity of hypertension as measured by blood pressure." (PMID 21526095, 2010). "Moreover, it has been found that SOD and CAT activity are decreased in L-NAME-induced hypertension." (PMID 34573119, 2021). "Lastly, in hypertension, vanillic acid exerts hypotensive effects by increasing nitric oxide metabolites, enhancing anti-oxidant enzyme activity (SOD, CAT, GPx), reducing lipid peroxidation, and modulating eNOS expression." (PMID 39850111, 2025). "In SHR rats, another model of hypertension, protocatechuic acid supplementation for 12 weeks significantly improved SOD and catalase." (PMID 37760002, 2023). "Activity of superoxide dismutase (SOD), catalase (CAT) and glutathione peroxidase was lower in patients with hypertension, which showed a decreased ability to overcome oxidative stress." (PMID 34685552, 2021). "Altered renal levels of CAT and GPX mRNA were found in kidneys before development of hypertension in spontaneously hypertensive rats." (PMID 33159023, 2020). "TGD can improve endothelial function in patients with hypertension via the mechanism of increasing GCH-PX and CAT content, remove excess oxygen free radicals, and prevent lipid peroxidation of vascular endothelial cells." (PMID 32089726, 2020). "In our study, we observed increased activity of antioxidant enzymes (↑ SOD, ↑ CAT, ↑ Px/GPx) in NWS, SWS, and erythrocytes in children with hypertension compared to the controls." (PMID 32204502, 2020). "In contrast, allicin increased the Nrf2 expression and consequently their target genes (CAT, SOD, and GPx), which led to decrease in hypertension, oxidative stress, ultimately improving cardiac structure and performance." (PMID 27990229, 2016). "A recent study reported on the decrease in the levels of SOD, and CAT, and an increase in the plasma levels of MDA with hypertension." (PMID 26267795, 2015). "PEG-catalase prevents the markedly increased vascular and urinary H2O2 levels and rise in blood pressure in hypertension induced by adenosine receptor blockade." (PMID 24533120, 2014). "Catalase, an H2O2 detoxifying enzyme, has been shown to prevent hypertension induced by the infusion of H2O2 in the renal medulla." (PMID 24533120, 2014). "Long-time oxidative stress can consume antioxidants and reduce SOD, CAT, and GSH-Px levels in cardiovascular diseases in general, and, especially, in arterial hypertension." (PMID 23533529, 2013). "The reduced levels of MDA, PC, CAT, SOD-1, POD, GHR, and GST in the kidneys of a 5-week-old animal model for hypertension may be attributed to several factors." (PMID 39513878, 2024). "Our results show that hypertension increased MDA concentration and reduced catalase activity." (PMID 39337885, 2024). "In vivo, MAOA was induced during aging and hypertension but the expression of the corresponding serotonin uptake receptor (SLC6A4) was reduced and enzymes that reduce either oxidative stress (CAT) or accumulation of 5-hydroxyindolacetaldehyde (ALDH2) were induced." (PMID 37371593, 2023). "Concomitant hypertension was observed in 98.4% and 100.0% of the patients in the CAT and non-CAT groups, respectively (P = 1.00)." (PMID 37198559, 2023).
Hypertension (continued). "Despite the strengthened antioxidant barrier (↑ SOD, ↑ CAT, ↑ Px/GPx, ↑ UA, ↑ TAC), in children with hypertension we observed an increase in oxidative damage to proteins (↑ AGE, AOPP) and lipids (↑ MDA), not only at the central level (plasma), but also in NWS and SWS." (PMID 32204502, 2020). "Similarly, CAT activity in NWS, SWS and erythrocytes, and Px activity in SWS and blood, were considerably higher in children from the hypertension group." (PMID 32204502, 2020). "Although we did not evaluate the rate of free radical production directly, our hypothesis may be confirmed by a positive correlation between the concentration/activity of antioxidants (SOD, CAT, UA) and TOS levels in children with hypertension." (PMID 32204502, 2020). "The odds of hypertension and its complications increased (p < 0.001) with an increase in BMI, Na+/K+, hs-CRP, MDA, and ferritin and a decrease in estimated glomerular filtration rate (eGFR), glutathione, superoxide dismutase, and catalase." (PMID 33489353, 2020). "Theexcessive production of TBARS and decreased CAT activity in the left ventricle and left(clipped) kidney in 2K1C SED rats was probably due to the increased levels of Ang IIthat develop in this model of hypertension." (PMID 26270472, 2015). "Although different studies have shown that in hypertension CAT activity is low, in our study CAT activity showed no significant change in SAH, MV, and TA when compared to C subjects." (PMID 25101153, 2014). "The synthetic mimetic of catalase and SOD used here, Euk134, has been used as an anti-oxidant in vivo for a variety of outcomes ranging from prevention of heart failure post-hypertension to provision of pain relief in situations where ROS accumulation has been implicated in the pathology." (PMID 25528158, 2014). "The reduced level of antioxidants (GSH) and antioxidant enzymes (catalase, SOD, and GST) in the renal and myocardial tissue of L-NAME hypertensive rats along with increased serum levels of urea, further support the harmful effect of hypertension vital organs like the heart, and kidney." (PMID 39171117, 2024). "Therefore, oxidative stress biomarkers have a positive association with hypertension and a negative relationship with plasma antioxidant activity, as reflected by the activity of enzymes such as SOD and CAT." (PMID 37927493, 2023). "In elderly primary essential hypertensive patients, administration of 5 mg/day of melatonin improved their antioxidant defense functions, as demonstrated by a significant increase in superoxide dismutase (SOD) 1 and catalase activities as well as a reduction in the serum malondialdehyde level." (PMID 35087617, 2022). "Furthermore, in experimental hypertension cases, increases in plasma MDA, protein carbonyl, and vascular superoxide production and reductions in plasma superoxide dismutase (SOD) and tissue catalase (CAT) activity have been observed in L-NAME-induced hypertensive rats." (PMID 33557258, 2021). "Moreover, TOS correlated positively with CAT and UA in SWS of children with hypertension." (PMID 32204502, 2020). "Reduced activity of two major antioxidant enzymes (Cu,Zn-SOD and CAT) as well as decreased potency of nonenzymatic antioxidants, such as GSH and vitamins C and A, were observed in the rat hearts in both models of hypertension, as has been shown elsewhere." (PMID 30223427, 2018). "However, MAP was not normalized to control levels in response to PEG-catalase, suggesting that H2O2 is not solely responsible for hypertension in established CKD." (PMID 24533120, 2014).
Sepsis (71 papers, 2007 to 2025). Sepsis is defined as life-threatening organ dysfunction caused by a dysregulated host response to infection. "Catalase upregulation appears to correlate with improved outcomes in various sepsis-associated organ injuries." (PMID 41293242, 2025). "To evaluate the oxidative stress parameters within sepsis‐associated AKI, we measured the content of ROS, malondialdehyde (MDA), glutathione (GSH) and determined the activities of SOD and catalase (CAT) in the kidney of sepsis‐associated AKI rats." (PMID 32827242, 2020). "We measured several parameters of oxidative stress, including levels of ROS, MDA, GSH and the activities of SOD and CAT, and found the oxidative stress caused by sepsis‐associated AKI was reduced by up‐regulation of circVMA21." (PMID 32827242, 2020). "Nevertheless, phlorizin reduced catalase activity in lung of rats with sepsis, suggesting an additional risk for lung damage development promoted by the oxidative stress under direct or indirect effects of the inhibitor of SGLT1 co-transporter." (PMID 31536570, 2019). "In sepsis, miR-122-5p level is increased, which reduces the activities of antioxidant enzymes such as catalase (CAT), superoxide dismutase (SOD) and glutathione peroxidase (GSH-px), leading to the generation of ROS and oxidative stress in cardiomyocytes." (PMID 40041174, 2025). "For instance, AKG alleviates lipopolysaccharide-induced sepsis in piglet spleens by elevating catalase (CAT), total superoxide dismutase (T-SOD), glutathione (GSH), and glutathione peroxidase (GPX) levels." (PMID 40298808, 2025). "Catalase-based EMNMs are capable of realizing the rapid diagnosis of sepsis and deeper tissue penetration for tumor treatment." (PMID 39896991, 2025). "In sepsis, mitochondrial ROS generation is significantly increased, whereas the production of antioxidant proteins such as CAT, superoxide dismutase, and glutathione peroxidase is greatly decreased, and lipid peroxidation products such as MDA are increased." (PMID 41294012, 2025). "In the group with CLP-induced sepsis, there was a substantial decrease in CAT activity, indicating a significant impact of sepsis on antioxidant enzyme levels, compared to the control group." (PMID 38326366, 2024). "Catalase, superoxide dismutase, and glutathione peroxidase activities were lower in the sepsis group compared to the sham-operated (control) group." (PMID 36648023, 2023). "Increased MDA and MPO levels and decreased SOD and CAT activities demonstrate sepsis-induced ovarian tissue damage in the present study." (PMID 36648023, 2023). "Compared with those in the sepsis group, the levels of IL-6, IL-1β and TNF-α were decreased (P < 0.05), the MDA content was decreased, with the SOD and CAT activities increasing in the sepsis + DMOG group (P < 0.05)." (PMID 35576220, 2022). "For the first time, we identified that CSO also has a neuroprotective effect against sepsis, maintaining the peroxisomal antioxidant enzyme activities of catalase and GPx." (PMID 36233157, 2022). "As for COS, it was found to alleviate the decrease of GSH and catalase (CAT) activities as well as the increase in malondialdehyde (MDA) levels in the organs of mice with lipopolysaccharide (LPS)-induced sepsis." (PMID 35743209, 2022). "Studies have pointed out that sepsis-induced CAT and SOD activity decreased significantly and MDA activity increased significantly." (PMID 34115555, 2021). "We report herein a treatment for sepsis based on PEGylated catalase, which can effectively break down hydrogen peroxide, a key component of ROS that is chemically stable and able to diffuse around the tissues and form downstream ROS." (PMID 34888304, 2021). "Several studies have shown that the SOD/CAT ratio increases significantly under LPS stimulation or sepsis in multiple organs and tissues." (PMID 34926535, 2021).
Sepsis (continued). "We found that sepsis‐associated AKI markedly increased the levels of ROS and MDA, but decreased the level of GSH and the activities of SOD and CAT in the kidney of the rats." (PMID 32827242, 2020). "In a previous study, the prognostic potential of the antioxidant enzymes superoxide dismutase (SOD) and catalase (CAT) was evaluated in sepsis." (PMID 32952850, 2020). "In a rat model of sepsis, LA treatment reduces lipid peroxidation in the lung by maintaining CAT and increasing SOD, GPx and CAT concentration." (PMID 32629814, 2020). "In a murine model of sepsis gallic acid was able to completely restore the lipid peroxidation whereas levels of CAT and SOD were partially restored." (PMID 27776518, 2016). "The change of catalase activity in sepsis treatment group was 0.33 ± 0.03 mM H2O2/min/mg as compared to SO treatment group, that is, 0.72 ± 0.04 mM H2O2/min/mg." (PMID 25018890, 2014). "In this study, CFE also markedly upregulated the activities of SOD, CAT, and GPx, which were observed to be markedly decreased in sepsis-induced ALI rodents and in the ALI patients clinically." (PMID 25214712, 2014). "Collectively, these studies underscore catalase as a multifaceted therapeutic agent in sepsis." (PMID 41293242, 2025). "Clinical and preclinical studies on catalase and glutathione activity and effects in sepsis." (PMID 41293242, 2025). "Catalase concentrations were negatively correlated with the updated sepsis score (r = −0.60)." (PMID 39854109, 2025). "GLP-1 receptor agonists exhibit potent antioxidant effects in sepsis by enhancing the expression and activity of key enzymes, such as superoxide dismutase (SOD), glutathione peroxidase (GPx), and catalase, which effectively neutralize ROS that are major mediators of cellular injury during sepsis." (PMID 41357527, 2025). "Furthermore, comprehensive reviews of antioxidant therapies have emphasized the relevance of catalase and other ROS-scavenging enzymes in mitigating the molecular cascades triggered by oxidative and nitrosative stress during sepsis." (PMID 41293242, 2025). "An animal experiment using sepsis rat model demonstrated that obese rats with sepsis display oxidative stress mainly in the lung and liver reflected by an oxidative damage to lipids and proteins and an imbalance of superoxide dismutase and catalase levels." (PMID 39348397, 2024). "Co/PMCS could mimic superoxide dismutase (SOD), catalase (CAT), and glutathione peroxidase (GPx) to rapidly scavenge reactive oxygen and nitrogen species for the treatment of bacterial-induced sepsis." (PMID 36080194, 2022). "The SOD/CAT ratio showed similar changes in the kidney model of sepsis." (PMID 34926535, 2021). "Herein, we explore the use of PEG-conjugated catalase as a therapeutic treatment for sepsis." (PMID 34888304, 2021). "It was described that acupuncture therapies could reduce content and activity of MDA, increase SOD activity, and upregulate CAT in sepsis animals, indicating that acupuncture at ST36 might be able to reduce oxidative stress during sepsis." (PMID 32215037, 2020). "However, sepsis promoted increase of catalase activity in lung tissue, indicating that balance can be maintained due to high levels of this antioxidant enzyme." (PMID 31536570, 2019). "We hypothesized that treatment with EUK-134 (manganese-3-methoxy N,N'-bis(salicyclidene)ethylene-diamine chloride), a compound with superoxide dismutase and catalase activity, attenuates the vascular manifestations of sepsis in vivo." (PMID 25815596, 2015). "In sepsis, endogenous antioxidant enzyme systems can be depleted within hours, with a 46–83% loss of activity in SOD and GPX, just 12 hours into sepsis, and a 52% reduction in the somewhat more resistant liver catalase." (PMID 18836533, 2007).